IL6 (interleukin 6)
Diseases named in the same sentence as IL6 in open-access papers (continued):
Sharing a sentence is not in itself a finding about the gene and the disease.
Obesity (continued). "For instance, obesity-related factors such as elevated levels of pro-inflammatory cytokines (e.g., IL-6, TNF-α) and adipokines (e.g., leptin) may promote an immune-stimulatory environment that facilitates a stronger anti-tumor response when ICIs are administered." (PMID 40040878, 2025). "Interestingly, an in vivo mouse study reported that IL-6 secretion from adipocytes derived from donors with obesity could stimulate adipose tissue macrophages, leading to IL-4 signaling and contributing to an anti-inflammatory environment." (PMID 40395977, 2025). "However, only IL-6, leptin, adiponectin, and resistin serum levels were found to be significantly associated with diabetes without obesity, after adjusting for age." (PMID 40095937, 2025). "Specifically, it downregulates pro-inflammatory cytokines (e.g., TNF-α, IL-1β, and IL-6) while upregulating anti-inflammatory IL-10 and tight junction proteins (e.g., ZO-1 and OCLN), thereby reducing systemic inflammation and metabolic endotoxemia associated with obesity." (PMID 41365537, 2025). "Obesity induces macrophage infiltration into adipose tissue and dysregulated adipokine secretion, leading to persistent elevation of inflammatory cytokines such as interleukin-6 (IL-6), tumor necrosis factor-alpha (TNF-α), and C-X-C motif chemokine ligand 10 (CXCL10)." (PMID 41441521, 2025). "Obesity associated with T2DM further amplifies this process by increasing the production of proinflammatory mediators such as tumor necrosis factor-alpha (TNF-α) and interleukin-6 (IL-6), while reducing adiponectin levels, a hormone with anti-inflammatory and insulin-sensitizing properties." (PMID 41462693, 2025). "Obesity is characterized by a chronic low-grade inflammation that affects thyroid function through excess cytokines and inflammatory markers—such as interleukin-1 (IL-1), interleukin-6 (IL-6), and tumor necrosis factor-alpha (TNF-alpha)—produced by enlarged adipose tissues." (PMID 41477173, 2025). "Taken together, our findings suggest that IL-6 and RBP4 may function as biomarkers of poor prognosis and may represent potential therapeutic targets, particularly in CRC cases linked to inflammation and obesity." (PMID 41007818, 2025). "In addition to anti IL-6 mABs, high IL-6 asthma with concomitant obesity and metabolic dysfunction may see further benefits with weight loss and management of metabolic diseases." (PMID 39714726, 2025). "In the context of obesity and insulin resistance, its clinical utility lies in detecting low-grade metabolic inflammation arising from excess adipose tissue—particularly visceral adiposity—through sustained cytokine release (e.g., IL-6) that stimulates hepatic CRP synthesis." (PMID 41305609, 2025). "Obesity further contributes to systemic low-grade inflammation, especially via visceral fat accumulation and metabolic dysfunction, leading to increased levels of IL-6, C-reactive protein, and tumor necrosis factor-α (TNF-α), which can trigger or worsen airway hyperresponsiveness." (PMID 40933690, 2025). "However, human myotubes exposed to TNF-a show increased IL-6 secretion, suggesting that muscle may also contribute to increased circulating IL-6 levels in people with obesity and T2D." (PMID 40171198, 2025). "TNF-α plays a different role in obesity, and it can cause an increase in a person’s glucose resistance and obesity/T2DM, a change in adipogenesis, and lipolysis, thus increasing other cytokines production (such as MCP-1, IL-6) which, in turn, will aggravate systemic inflammation." (PMID 40244195, 2025). "Obesity contributes to this pro-inflammatory milieu by promoting the release of cytokines such as interleukin-6 (IL-6), tumor necrosis factor-alpha (TNF-α), and C-reactive protein (CRP), which may adversely affect both the synovial environment and the fibrotic response within the joint capsule." (PMID 41007680, 2025).
Obesity (continued). "Additionally, the chronic low-grade inflammation in obesity, characterized by an increase in pro-inflammatory cytokines such as IL-6) and tumor necrosis factor-α, along with C-reactive protein, creates a state that may precipitate insulin resistance." (PMID 39996060, 2025). "Thus, on one hand, chronically elevated circulating IL-6 levels may contribute to impaired glucose homeostasis in obesity." (PMID 40171198, 2025). "In obesity, macrophages infiltrating adipose tissue form corona-like structures surrounding adipocytes, leading to the overproduction of adipokines, which comprise pro-inflammatory mediators, such as interleukin-1β (IL-1β), interleukin-6 (IL-6), and tumor necrosis factor-alpha (TNF-α)." (PMID 40427531, 2025). "Furthermore, obesity is associated with chronic inflammation and elevated levels of cytokines, such as TNF-α, interleukin-1 beta (IL-1β), interleukin-6 (IL-6), and adipokines (e.g., leptin), which support tumor cell proliferation, angiogenesis, and TME modulation." (PMID 41228278, 2025). "Obesity is associated with inflammatory alterations; in the present study, subjects with positive HAdV-36 seroprevalence, normal weight, overweight, and obesity had high levels of IL-6, while, in subjects with low weight, the IL-6 levels were not significant." (PMID 40136420, 2025). "Considering our findings (reduction in TNF-α without alterations in IL-6), we can suggest that ST may have partially attenuated the obesity-associated inflammatory state without impacting the secretion of pro-metabolic myokines." (PMID 40862455, 2025). "In T2D, obesity-related inflammation and the modifying effects of diverse therapies may mask such associations, leading to the absence of significant differences in IL-6 concentrations in our cohort." (PMID 41010714, 2025). "Besides the overproduction of cytokines such as IL-6 and TNF-α within the inflamed mammary microenvironment, which has deleterious effects on mammary gland function, obesity is linked to increased synthesis of serotonin in the mammary gland by upregulating tryptophan hydroxylase 1 (TPH1)." (PMID 40868103, 2025). "This disruption not only impacts the adipogenic capacity but may also contribute to the proangiogenic features of obesity-derived APCs, as seen in their increased IL-6 expression and activation of Notch signaling pathways, further linking chronic inflammation to adipose tissue dysfunction." (PMID 40699742, 2025). "Given the increased expression of TNF and IL-6 noted in mice with high-fat diet-driven obesity phenotype, it is assumable that the inflammation observed in AO rats might be related to their proneness to obesity." (PMID 40177400, 2025). "Thus, white adipose tissue in obesity secretes a spectrum of proinflammatory molecules, including IL‐6, IL‐8, IL‐17, IL‐23, monocyte chemoattractant protein‐1 (MCP‐1), plasminogen activator inhibitor 1 (PAI‐1), establishing systemic obesity's chronic low‐grade inflammation." (PMID 39760506, 2025). "Interfaces with obesity and associated metabolic disorders: Prospectively test whether targeting inflammation/energy metabolism (e.g., NLRP3/IL-6 pathways, statins/metformin/colchicine) disrupts the obesity–CHIP feedback loop and improves cardiometabolic outcomes." (PMID 41516113, 2025). "A dysbiosis in the gut microbiome as the result of obesity leads to a change in metabolites such as SCFA that cause a pro-inflammatory state characterized by increased levels of pro-inflammatory cytokines such as IL-1, IL-6, and TNF-α, the so-called “inflammatory triad”." (PMID 40551741, 2025). "Obesity, especially the VSF compartment, has been associated with a low-grade chronic inflammatory state due to the activation of the non-specific immune system, which increases the production of pro-inflammatory cytokines such as tumor necrosis factor-alpha and Interleukin-6." (PMID 39578337, 2025).
Obesity (continued). "However, only IL-6, leptin, adiponectin, and resistin serum levels were found to be significantly associated with diabetes without obesity, even after adjusting for sex (Model 2) or age (Model 3)." (PMID 40095937, 2025). "Furthermore, IL-6 is central in the transition from acute inflammation to a chronic inflammatory state of disease, and it contributes to chronic inflammation in conditions such as obesity and insulin resistance." (PMID 40003433, 2025). "Furthermore, obesity‐induced inflammation results in the production of pro‐inflammatory cytokines, such as interleukin‐6 (IL‐6), tumor necrosis factor‐alpha (TNF‐α), and C‐reactive protein (CRP), which contribute to an inflammatory TME conducive to cancer progression." (PMID 40922069, 2025). "For instance, activity increases interleukin-6, boosting anti-inflammatory cytokine secretion and dampening the HPA axis response to stress, potentially alleviating mental stress and preventing conditions associated with systemic inflammation (e.g., obesity, cardiovascular disease)." (PMID 40603677, 2025). "Obesity, with its characteristic dysfunctional adipose tissue and adipokine dysregulation, creates chronic systemic inflammation characterized by elevated circulating IL-6, TNF-α, and other pro-inflammatory cytokines that act as paracrine and endocrine signals influencing prostate tissue." (PMID 41555998, 2025). "For instance, the identification of FTO or PPARG risk alleles could guide early lifestyle interventions in individuals at high risk for obesity or type 2 diabetes, while variants in COL1A1 or IL6 may allow the identification of increased susceptibility to tendon or ligament injuries." (PMID 41300761, 2025). "Furthermore, adipose tissues, especially VATs, produce excess IL-6 in obesity." (PMID 41153608, 2025). "A vast number of epidemiological, genetic, rodent, and human in vivo and in vitro studies have investigated the putative role of action/lack of action of IL-6 in the pathogeneses underlying obesity, insulin resistance, β-cell destruction, type 1 diabetes, and type 2 diabetes." (PMID 38504163, 2024). "Taken together, these findings support the possibility that direct inhibition of the IL-6 signaling axis offers the potential to bridge such activities, one of the primary measures of success in heart failure-specific, especially arrhythmia-specific, therapy in obesity." (PMID 39125976, 2024). "Furthermore, both IL-1RA and IL-6 have been positively associated with hypoxia in animal and human models, as well as measures of obesity and insulin resistance in nondiabetic adults." (PMID 39201638, 2024). "The atherosclerotic process that causes subsequent CAD is associated with increased IL-6 production due to inflammation, and on the other hand, increased IL-6 values, determined by extrinsic factors such as obesity, social stress, smoking, and pollution, may increase the atherosclerotic risk." (PMID 39330316, 2024). "Therefore, we examined whether CK can lower the mRNA level of inflammatory cytokines such as TNFα and IL-6 to ascertain its impact on obesity-mediated inflammation." (PMID 39859981, 2024). "Furthermore, in the context of metabolic disorders such as obesity, γδ17 cells have been observed to exacerbate inflammation and insulin resistance through heightened cytokine production, including IL-6 and TNF-α, and the recruitment of proinflammatory M1 macrophages." (PMID 38774876, 2024). "This inhibition was associated with reduced levels of pro-inflammatory cytokines, including interleukin 6 (Il6), tumor necrosis factor-alpha (Tnfα), and interleukin 1beta (Il1β), underscoring the potential of TC extract as a therapeutic intervention for mitigating obesity-induced inflammation." (PMID 39683572, 2024). "Elevated levels of interleukin (IL)-6 and tumor necrosis factor (TNF)-α have been associated with dysregulation of serotonergic and GABAergic systems, which may exacerbate mood disorders symptoms in individuals with obesity." (PMID 39839130, 2024).
Obesity (continued). "Similarly, leptin knockout in obesity-derived adipocytes reduced tumor growth of triple negative breast cancer (BT20) which was associated with reduced expression of angiogenesis-promoting genes (e.g., SERPINE1, SNAI2, IL-6, TWIST1, and PTGS2)." (PMID 39439572, 2024). "In addition, in obesity, pro-inflammatory mediators (leptin, resistin, IL-6, and TNF-α) may promote adipose tissue dysregulation and systemic insulin resistance." (PMID 39065815, 2024). "In addition, a considerable reduction in obesity-associated low-grade chronic inflammation (TNF-α, IL-6, IL-1β plasma levels) could be observed." (PMID 39765824, 2024). "It has been proposed that an increase in the secretion of interleukin-6 (IL-6) and tumor necrosis factor-alpha (TNF-α) in adipose tissue under conditions of obesity-induced insulin resistance could underlie the associations of insulin resistance with endothelial dysfunction and coagulopathy." (PMID 39199353, 2024). "Finally, IL6 and CCL4 were confirmed as the hub genes associated with both obesity and GC." (PMID 39011399, 2024). "Common risk factors, such as obesity, aging, and chronic inflammation have been involved in the probable mechanisms of the relation between hypertension and KOA, in addition to the vital role played by the proinflammatory cytokine interleukin-6 in both diseases." (PMID 39472918, 2024). "Our main objective was to evaluate the levels of adiponectin, leptin, TNFα, IL6, and IGFs 1 and 2 in endometrial cancer patients compared to control patients with benign gynaecological conditions and to assess their relationship with obesity using the WHO BMI classification." (PMID 38339282, 2024). "However, the potential therapeutic benefits and efficacy of selectively targeting IL-6 trans-signaling (olamkicept) for prevention of VT in obesity are unknown." (PMID 39063055, 2024). "Perhaps, as suggested by other researchers, the association between IR and obesity is due to chronic inflammatory responses caused by increased synthesis and release of pro-inflammatory factors such as TNF-α (tumor necrosis factor-α), IL-6 (interleukin-6), and C-reactive protein." (PMID 38392069, 2024). "The results showed a significant association (P < 0.05) between NASH- and obesity-related parameters and the gut microbiota of GAN-fed mice, including body weight, total fat, TC, LDL, AST, liver weight, NAS, steatosis, lobular inflammation, hepatocyte ballooning, TNF-ɑ, IL-1β, and IL-6." (PMID 38018983, 2024). "It is established that obesity is associated with a state of chronic inflammation in the patient, characterized by the accumulation of M1-polarized macrophages, Tregs, and the secretion of proinflammatory factors, including TNF-α, IL-6, IL-1β, and leptin, which have all been linked to CRC." (PMID 39201522, 2024). "Regarding obesity, they reported some effects of adiponectin and leptin in cancer progression (the levels of these two adipokines are inversely and directly related to obesity) and they analyzed the role of a pro-inflammatory cytokine such as IL-6 and TNF-α in cancer development." (PMID 39410050, 2024). "Thus, a mouse model with a conditional cell-specific overactivation of IL-6 signaling in macrophages could be a promising model to further investigate the role of IL-6 in obesity." (PMID 38482013, 2024). "Therefore, the blockade of IL-6 in concert with other known molecular drivers of obesity-related ventricular arrhythmias may provide a more favorable clinical outcome than targeting IL-6 alone." (PMID 39125976, 2024). "Thus, understanding the link between obesity, IL-6 trans-signaling, and ventricular arrhythmias may have broad clinical implications for many heart diseases." (PMID 39125976, 2024). "The present study showed that the BMI positively correlated with CSF IL‐6 in nonclinical participants, and the overweight participants showed higher CSF IL‐6 levels than the nonoverweight ones, suggesting that obesity/overweight is associated with central inflammation." (PMID 39401137, 2024).
Obesity (continued). "In this study, 6‐week‐old C57BL/6J male mice fed with HFD for 14 weeks showed increased obesity‐related indexes including alanine aminotransferase, aspartate aminotransferase, total cholesterol, total triglyceride, free fatty acids, lipopolysaccharides, IL‐6, and TNFα." (PMID 38479983, 2024). "However, other work has found that vitamin D intake caused an increase or no significant change in IL‐6 levels after supplementation in a population affected by dyslipidemia, obesity, or diabetes." (PMID 39267468, 2024). "An association between obesity and OA is related not only to the increased biomechanical overload, but also to the systemic effects of obesity, including low-grade inflammation with increased levels of proinflammatory cytokines (IL-1β, TNF-α, and IL-6) and reactive oxygen species, etc.." (PMID 38791302, 2024). "This suggests that higher IL‐6 and TNF‐α levels in PCOS may be associated with IR, HA and obesity." (PMID 39036884, 2024). "At the same time, the hyperactivation of glucocorticoid receptors can cause inflammatory response, which may explain why levels of the pro-inflammatory cytokines tumor necrosis factor-α and interleukin-6 were significantly higher in the presence of stress-induced obesity than in its absence." (PMID 39539712, 2024). "In an in vitro model of obesity-associated cellular stress, exposure of preadipocytes and adipocytes to palmitate and TNF-α significantly increased markers of hypoxia (HIF-α, GLUT1, VEGF), ER stress (sXBP1, CHOP, BiP/GRP78), and inflammation (IL-6, MCP-1, and TNF-α)." (PMID 39063184, 2024). "However, IL-6 appears to protect from pancreatic islet damage in obesity." (PMID 38474057, 2024). "TNF-α plays a complex role in obesity, being associated with insulin resistance/type 2 diabetes, alteration in adipogenesis, increased lipolysis, and amplification of systemic inflammation by stimulating the production of other cytokines such as MCP-1 and IL-6." (PMID 38257150, 2024). "Weight loss has been shown to reduce pro-inflammatory markers present in the chronic low-grade inflammatory state associated with obesity, including CRP, IL-6 and TNF-a (Christiansenet al., 2010;Marfellaet al., 2004;Moelleret al., 2016) and may thereby help manage LC symptoms." (PMID 39145102, 2024). "It has been documented that obesity in BC is directly linked with CRF, and this association is probably attributed to the high levels of circulating inflammatory cytokines, i.e., tumor necrosis factor-alpha (TNF-alpha) and interleukin-6 (IL-6), as well as blood fatty acid imbalance." (PMID 38398193, 2024). "The tissue inflammatory state during obesity may be caused by TLR-4/NF-κB pathway activation in macrophages via FFA action, which promotes the synthesis and secretion of proinflammatory cytokines, including IL-6, TNF-α, IL-1β, and IL-18." (PMID 37372966, 2023). "Obesity was associated with decreased serum levels of Eotaxin and KC, and elevated serum levels of G-CSF, TNF-α in offspring mice, while KD alone was associated with elevated serum levels of G-CSF, IL-1b, IL-6, RANTES, TNF-α and decreased serum levels of IL-1a, IL-9, IL-12 (p70)." (PMID 37686855, 2023). "Indeed, fat tissues are metabolic/endocrine organ that secretes adipokines, chemokines, and proinflammatory cytokines such as tumour necrosis factor-alpha (TNF-α), and interleukin-6 (IL-6), and others, thus play an important role related to obesity, and inflammation." (PMID 37861729, 2023). "In the present cohort, obesity-linked variables, such as diabetes, dyslipidemia (low HDL cholesterol and high triglyceride levels) and elevations in systemic inflammatory markers (CRP, IL-6 and IL-18), were more common among individuals with complete fatty degeneration of thymus." (PMID 37653480, 2023). "Interestingly, patients with a high visceral to total fat ratio also had higher levels of IL-6 and tumor necrosis factor α, suggesting that the detrimental effects of obesity may be mediated by inflammation." (PMID 37225730, 2023).